TNF (tumor necrosis factor)
Diseases named in the same sentence as TNF in open-access papers (continued):
Sharing a sentence is not in itself a finding about the gene and the disease.
Obesity (continued). "Marked increases in the expression of TNF-α were identified in obese mouse models, and were linked to obesity and insulin resistance." (PMID 20414465, 2010). "Obesity is associated with chronic low-level inflammation and high levels of TNF-α, which is produced by subcutaneous adipocytes." (PMID 20822522, 2010). "Many studies reported a central role of TNF-α and other proinflammatory cytokines in the development of obesity-associated insulin resistance and fatty liver." (PMID 20953409, 2010). "Growing evidence shows elevation of plasma IL-6 and TNF-α concentrations in depressed and diabetic patients and IL-6 represents the higher association with obesity and insulin resistance." (PMID 20490354, 2010). "In humans, adipose tissue TNF-α expression correlated with BMI, percentage of body fat and hyperinsulinemia, whereas weight loss decreased TNF-α, underlining the role of this cytokine in obesity induced insulin resistance." (PMID 19545451, 2009). "Adipocyte enlargement, as observed in obesity, is associated with dysfunctional fat cells which over-express and secrete excessive amounts of leptin, IL-6, TNFα, resistin, MCP-1 and FFA while under secreting adiponectin." (PMID 19656356, 2009). "Free fatty acids (FFA) and tumor necrosis factor alpha (TNF-α) have been implicated in the pathogenesis of many obesity-related metabolic disorders." (PMID 17498300, 2007). "Cardiovascular diseases, diabetes, obesity, cancer and other pathologies are associated with increased production of thromboxane A2, leukotriene B4, Il-1β, IL-6 and TNF." (PMID 17313679, 2007). "TNF-α is produced by adipocytes also in response to obesity, causing increased expression of the transcription factor NFκB, and leading eventually to down-regulation of the insulin receptor and the major insulin-responsive glucose transporter GLUT4." (PMID 17107852, 2006). "Moreover, obesity is associated with increased production of TNF-α and elevated expression of its soluble receptors." (PMID 41602238, 2026). "Background and Objectives: The pathogenesis of liver steatosis is associated with obesity and systemic inflammation, particularly in subjects with body mass index (BMI) above 40 kg/m2 and altered serum levels of tumor necrosis factor alpha (TNF-α) and interleukin-10 (IL-10)." (PMID 42195075, 2026). "Therefore, we aimed to determine if TNF signaling is associated with adipose tissue reduction following bariatric surgery in individuals with obesity." (PMID 41508774, 2026). "In summary, TNF-α is a pro-inflammatory cytokine secreted by macrophages in a healthy environment, but it can also be secreted by adipose tissue in obesity, showing strong association with health issues such as insulin resistance, dyslipidemia, sarcopenia and cardiovascular conditions." (PMID 41141350, 2025). "M1 macrophages are commonly associated with metabolic dysfunction in obesity, as they secrete pro-inflammatory cytokines such as tumor necrosis factor alpha (TNFα), interleukin (IL)-1β, IL-12, and IL-23, which can disrupt insulin signaling and exacerbate systemic inflammation." (PMID 41226298, 2025). "Moreover, obesity-induced adipose tissue inflammation, characterized by elevated macrophage infiltration and pro-inflammatory cytokine production (e.g., TNF-α, IL-6), plays a crucial role in the pathogenesis of obesity-associated metabolic disorders." (PMID 40004080, 2025). "Obesity is frequently linked with adipose tissue that exhibits hypoxic environments and the demise of adipocytes, subsequently prompting the release of inflammatory mediators, including TNF-α, IL-6, and MCP-1." (PMID 41383623, 2025). "Only TNF-α and leptin were associated with metabolic syndrome (MetS) among the obesity group." (PMID 39837875, 2025).
Obesity (continued). "Activated microglia and astrocytes, responding to obesity-associated inflammation, adopt prolonged pro-inflammatory states, releasing interleukin 1β (IL-1β), IL-6, TNF-α, reactive oxygen species (ROS), and proteases such as matrix metalloproteinases (MMPs) and cathepsins." (PMID 41155642, 2025). "TNF-α has been shown to causally mediate Wnt signaling associated with obesity, indicating that inflammation-driven Wnt signaling may be a mechanism underlying colorectal carcinogenesis linked to obesity." (PMID 40406485, 2025). "One argument is that other adipokines (such as IL-6, TNF-α and leptin) predominate in the inflammatory profile in higher obesity states, and resistin, which is more closely linked to immune cell activation, may not scale up further with additional adiposity." (PMID 41011232, 2025). "TNF-α is regarded as an important factor in obesity-associated insulin resistance." (PMID 40048497, 2025). "Low-grade inflammation is a hallmark of adult obesity, with adipose tissue depots producing and secreting inflammatory mediators, most frequently IL-6, interleukin-8 (IL-8), interleukin-1 receptor antagonist (IL-1Ra), and TNF-α, among others." (PMID 40426748, 2025). "Hence, obesity alone and type 2 diabetes with obesity were significantly associated with TNF-α, IL-6, leptin, adiponectin, resistin, and ALR even after adjusting for sex (Model 2) or age (Model 3)." (PMID 40095937, 2025). "Correspondingly, elevated pro-inflammatory immunological markers such as Interleukin (IL)-1β, Interleukin-6, and Tumor Necrosis Factor-alpha (TNF-α) have been linked to obesity as well as to post-COVID condition (PCC), likely produced by overactivated monocytes and macrophages." (PMID 41323348, 2025). "Adipose Tissue and Metabolic Effects: SGLT2is mitigate obesity-associated adiposopathy by shifting macrophage polarization (M1 to M2), reducing proinflammatory cytokines (TNF-α, IL-6), and enhancing adipose tissue browning (UCP1 upregulation) and mitochondrial biogenesis (via PGC-1α/PPARα)." (PMID 40863154, 2025). "However, the significant decrease in circulating TNF-α is an indication of reduced inflammation, which is consistent with the loss of fat and an important factor for individuals with obesity." (PMID 40219022, 2025). "In fact, obesity, itself indicating a chronic state of low-level inflammation, has been associated with generally elevated levels of pro-inflammatory cytokines, including IL-6, TNF, as well as iNOS detectable in serum." (PMID 40508229, 2025). "Given the emerging role of adipose tissue in the progression of sarcopenia, increased TNF‐α signaling may associated with coalescence of sarcopenia and obesity." (PMID 39764565, 2025). "The data showed that as the CDAI increases in subjects with obesity carrying the TNF-α risk allele (A), a more pronounced downward trend in insulin levels was observed, compared to those with the GG genotype, supported by a statistically significant interaction." (PMID 40732969, 2025). "Furthermore, obesity is characterized as a pro-inflammatory state, associated with elevated levels of pro-inflammatory cytokines, including tumor necrosis factor and interleukin-6." (PMID 41016748, 2025). "In the present review, two studies rated as having a low value of evidence found an association between obesity and higher amounts of salivary TNF-α, one involving Brazilian preschoolers with dental caries and the other comprising North American children aged 6 to 10 years." (PMID 40565251, 2025). "Furthermore, the chronic low-grade inflammation associated with obesity, mediated by cytokines such as tumor necrosis factor-alpha (TNF-α), released from hypertrophic adipocytes, reduces GnRH neuron responsiveness to stimulatory inputs like kisspeptin." (PMID 40755647, 2025). "Conversely, obesity is associated with increased IL-6, TNF-α, and IL-1β levels, creating a pro-inflammatory state that could contribute to depressive symptoms." (PMID 41375608, 2025).
Obesity (continued). "TNF-α is a cytokine elevated in obesity-associated inflammation." (PMID 41555998, 2025). "Although TNF-α has traditionally been associated with pro-inflammatory effects and metabolic dysfunction in obesity, its role may be more complex, particularly in the context of chronic exercise." (PMID 40729041, 2025). "Moreover, obesity associated inflammation, especially a rise in tumor necrosis factor alpha (TNFa) level, contribute to a reduction of taste cell proliferation, hence regeneration." (PMID 41047117, 2025). "TNF- or TNFR1-deficient mice are protected from HFD-induced obesity." (PMID 40961178, 2025). "Obesity, a significant risk factor for GD, highlights the role of adipose tissue as an endocrine organ secreting adipokines and pro-inflammatory cytokines like tumor necrosis factor α (TNF-α) and interleukin (IL) IL-6." (PMID 40941639, 2025). "Obesity is associated with a low-grade chronic inflammatory state, characterised by the elevation of pro-inflammatory cytokines, including but not limited to interleukin-6 (IL-6) and tumor necrosis factor-alpha (TNFα)." (PMID 40564637, 2025). "Then, potential effects of CCJ12 on adipokines (leptin and adiponectin), cardiovascular (sE-selectin and C-reactive protein), and inflammatory (MCP-1 and TNF-alpha) factors were studied, because these factors are also associated with obesity as well as other diseases." (PMID 40770283, 2025). "Obesity associated with T2DM further amplifies this process by increasing the production of proinflammatory mediators such as tumor necrosis factor-alpha (TNF-α) and interleukin-6 (IL-6), while reducing adiponectin levels, a hormone with anti-inflammatory and insulin-sensitizing properties." (PMID 41462693, 2025). "The study found that obesity, smoking, low albumin concentrations, higher baseline markers of disease activity, and development of immunogenicity were all associated with low drug concentrations and anti-TNF failure." (PMID 40004589, 2025). "TNF-α plays a different role in obesity, and it can cause an increase in a person’s glucose resistance and obesity/T2DM, a change in adipogenesis, and lipolysis, thus increasing other cytokines production (such as MCP-1, IL-6) which, in turn, will aggravate systemic inflammation." (PMID 40244195, 2025). "Obesity is a state of chronic low-grade inflammation, with adipose tissue acting as an active endocrine organ that produces proinflammatory cytokines such as TNF-α, IL-6, and leptin—all implicated in the pathophysiology of psoriasis." (PMID 41010661, 2025). "The reductions in CRP and TNF-α are clinically significant, given their established associations with cardiometabolic disorders, including cardiovascular disease, type 2 diabetes, and obesity." (PMID 41301508, 2025). "Perhaps TNF-α could be a more potent marker, better reflecting the chronic inflammation associated with obesity, and deserving of further investigation." (PMID 40565251, 2025). "Chronic inflammation from obesity causes the liver to release inflammatory factors like TNF-α, IL-1, and IL-6, which upregulate hepatic hepcidin synthesis and may reduce erythropoietin synthesis and activity." (PMID 40709336, 2025). "The modulation of the tumor microenvironment by obesity-associated molecules, including hormones and pro-inflammatory cytokines (e.g. TNF-α, IL-6) can play a key role in promoting tumor development and progression and, at the same time, in enhancing T-cells function and immune responses to ICIs." (PMID 41278286, 2025). "Similarly, obesity was linked with higher TNF-α and oxidative stress markers, adipocytokines and increased IL-6, IL-8 and IL-10 in some studies." (PMID 40076848, 2025). "It is suggested that sleep deprivation acts directly on the risk of being overweight/obesity through its role in sympathetic activation, increased cortisol secretion, and increased levels of interleukin and tumor necrosis factor via activation of the inflammatory cascade." (PMID 41347131, 2025).
Obesity (continued). "In another mechanistic study, the obesity-related adipose tissue secretes hormones and inflammatory substances such TNF-α and interleukin-6 (IL-6), which can raise the risk of osteoporosis by accelerating bone resorption and preventing the production of new bone." (PMID 40177287, 2025). "It is well established that obesity and T2D are associated with increased blood glucose and TNFα levels, which may activate NFκB signaling." (PMID 40002359, 2025). "Perhaps, as suggested by other researchers, the association between IR and obesity is due to chronic inflammatory responses caused by increased synthesis and release of pro-inflammatory factors such as TNF-α (tumor necrosis factor-α), IL-6 (interleukin-6), and C-reactive protein." (PMID 38392069, 2024). "As a metabolic pathogenic status, obesity is often accompanied by systemic chronic low-grade inflammation and elevated levels of immune markers such as leptin, IL-6, and TNF, which may influence tumor growth." (PMID 39165513, 2024). "Moreover, it has been demonstrated that some regions of the human genome, such as chromosomes 5q, 6p, 11q, and 12q, are associated with both asthma and obesity, containing genes encoding TNF-α, glucocorticoid receptor, or β2-adrenoceptor." (PMID 38542187, 2024). "In a mouse model of obesity associated with breast cancer, administration of fish oil in addition to a high-fat diet decreased the levels of inflammatory cytokines tumor necrosis factor-α and interleukin (IL)-6 and increased the levels of the anti-inflammatory cytokine IL-1026." (PMID 38228757, 2024). "Increased histone acetylation in the tumor necrosis factor (Tnfa) and monocyte chemotactic protein 1 (Mcp1/Ccl2) inflammatory cytokine genes has also been associated with fatty liver disease in mouse models of obesity." (PMID 38790268, 2024). "Also, the decreasing effect of V. agnus-castus leaf extracts on TNF-α and IL-6 levels, which are associated with obesity, has been proven." (PMID 39055496, 2024). "In addition, an increased secretion of cytokines such as TNF-α has been reported with obesity-associated adipose tissue enlargement." (PMID 38542788, 2024). "TNF-α was the first pro-inflammatory cytokine to be associated with obesity and insulin resistance." (PMID 39606781, 2024). "Increased white-adipose-tissue (WAT) content, which constitutes the hallmark of obesity, leads to enhanced secretion of adipokines, including leptin, resistin, interleukin 6 (IL-6), tumor necrosis factor-alpha (TNF-α), visfatin, vaspin, and retinol-binding protein 4 (RBP-4)." (PMID 38794651, 2024). "Elevated levels of interleukin (IL)-6 and tumor necrosis factor (TNF)-α have been associated with dysregulation of serotonergic and GABAergic systems, which may exacerbate mood disorders symptoms in individuals with obesity." (PMID 39839130, 2024). "Inflammation caused by an imbalance of interleukin 6, 8 and TNF-alpha secreted by adipose tissue is thought to weaken and dilate vessels and may explain the role of obesity in aneurysm formation and weight loss may reduce the aortic diameter." (PMID 38674307, 2024). "Pro-inflammatory cytokines like TNF-α and IL-6 are linked to obesity." (PMID 38473961, 2024). "C-reactive protein (CRP), adipocyte-derived metabolites, and inflammatory cytokines [such as tumor necrosis factor alpha (TNF-α), IL-1β, and IL-6] have been shown to play a role in inflammation associated with obesity, and in the development of insulin resistance." (PMID 38978699, 2024). "Moreover, this expression was positively correlated with insulin concentrations in plasma collected from fasting individuals, suggesting the involvement of TNF-α in insulin resistance, which is frequently associated with obesity." (PMID 39275140, 2024).
Obesity (continued). "In children with overweight/obesity, the levels of pro-inflammatory cytokines, particularly IL-5, IL-17A, IL-33, TNF-α, and leptin, were also elevated, which is consistent with previous findings, indicating chronic low-grade inflammation associated with obesity." (PMID 39902293, 2024). "Chronic ER stress, such as obesity, causes persistent inflammation in adipocytes and macrophages and induces the increased expression of the proinflammatory cytokines interleukin-6 (IL-6) and tumor necrosis factor alpha (TNFα)." (PMID 38732214, 2024). "Obesity-induced chronic inflammation contributes to a proinflammatory environment characterized by elevated levels of cytokines such as interleukin (IL)-6, IL-1β, and tumor necrosis factor-alpha (TNF-α), which are implicated in the pathogenesis of COVID-19." (PMID 39861827, 2024). "Additionally, both galectin-1 and galectin-3 were associated with IL-10 and TNF signaling, pathways previously related to galectins and with a role in obesity-related inflammation and lipid metabolism." (PMID 38777863, 2024). "TNF-α plays a complex role in obesity, being associated with insulin resistance/type 2 diabetes, alteration in adipogenesis, increased lipolysis, and amplification of systemic inflammation by stimulating the production of other cytokines such as MCP-1 and IL-6." (PMID 38257150, 2024). "Clinically, the elevated systemic levels of IL-6 and TNF-α are particularly concerning, since these pro-inflammatory molecules are directly associated with insulin resistance and hyperinsulinemia, which are common in individuals with obesity." (PMID 39125408, 2024). "Obesity is associated with chronic inflammation, characterized by the infiltration of immune cells that release pro-inflammatory cytokines such as Tumor Necrosis Factor-α (TNF-α) and Interleukin-6 (IL-6)." (PMID 39741884, 2024). "Additionally, the suppression of serum inflammatory markers (LPS and TNF-α) was linked to reduced consumption of a high-fat diet, contributing to the effective control of obesity." (PMID 38731751, 2024). "Furthermore, the inflammatory pathways activated in PsO, including increased TNF-α, IL-6, and other pro-inflammatory cytokines, are also implicated in the pathogenesis of obesity and metabolic syndrome." (PMID 39697959, 2024). "Obesity could trigger immune-inflammatory pathways, causing adipose tissue to release inflammatory cytokines like tumor necrosis factor-α and interleukin-6, which can impair brain function and precipitate depressive symptoms." (PMID 39957754, 2024). "In adipose tissue, TNF-α may be involved in the regulation of Nrg4 level which may be one of the causes of the reduced Nrg4 expression in obesity with chronic inflammation." (PMID 39162358, 2024). "Notably, the loss of TNF-alpha has been linked to improved insulin sensitivity and protection against obesity-related reduction in insulin receptor signaling in obese mice." (PMID 39120321, 2024). "Moreover, cardiovascular complications and atherosclerotic disease were frequently associated with DM and obesity, and IL-6 and TNF-α levels were elevated in human atheromatous lesions." (PMID 39408723, 2024). "The causal link between obesity and IR lies in the elevated levels of proinflammatory adipokines, such as IL-6 and TNF-α, released by adipose tissue following fat accumulation, which worsens tissue responses to insulin, thus resulting in T2D, dyslipidemia and hypertension." (PMID 38133765, 2024). "Fucosterol, a phytosterol derived from the marine brown algae Padina boryana, exhibited anti-inflammatory properties via dose-dependently down regulating pro-inflammatory cytokines (IL-1, IL-6, and TNF) and the Nrf2/HO-1 pathway and aid in the process of losing weight in obesity associated asthma." (PMID 37251328, 2023).